ZEB1 (zinc finger E-box binding homeobox 1)
Diseases named in the same sentence as ZEB1 in open-access papers (continued):
Sharing a sentence is not in itself a finding about the gene and the disease.
ischemic stroke (5 papers, 2009 to 2025). A stroke disorder caused by obstruction of blood flow to the brain, due to thrombotic (local blood clot formation) or embolic (due to a blood clot or other material traveling from another site) event. "ZEB1 was reported to function as a transcription factor associated with microglial regulation in ischemic stroke." (PMID 33771213, 2021). "In an acute ischemic stroke model, increased expression of ZEB1 reduces microglial reactivity and ameliorates brain damage." (PMID 41300781, 2025). "A previous study also indicated that a more ramified morphology of microglia with upregulated ZEB1 expression may enable microglia to react more accurately and quickly to a stimulus, resulting in improved regulation of inflammatory responses after ischemic stroke." (PMID 33771213, 2021). "Notably, ZEB1 has been shown to interact with GPR30, modulating inflammatory responses in ischemic stroke via TLR4/NF-κB pathway inhibition." (PMID 40726812, 2025).
myocardial infarction (5 papers, 2021 to 2026). Gross necrosis of the myocardium, as a result of interruption of the blood supply to the area, as in coronary thrombosis. "COL1A1 and COL3A1 mRNA as well as collagen cross-linking enzymes were found to be upregulated by the transcription factor Zinc Finger E-Box Binding Homeobox 1 (ZEB1) in the context of myocardial infarction." (PMID 37373151, 2023). "Long non-coding RNA-IH (LncRNA-IH) promotes post-myocardial infarction (post-MI) cardiac fibrosis and activates the TGF-β1/ZEB1 pathway." (PMID 41563538, 2026). "This study also confirmed significantly lower miR-590-3p expression and higher expression of ZEB1 mRNA in minipigs with myocardial infarction comparing to controls without MI." (PMID 34071976, 2021).
posterior polymorphous corneal dystrophy 3 (5 papers, 2016 to 2025). Any posterior polymorphous corneal dystrophy in which the cause of the disease is a mutation in the ZEB1 gene. "The ZEB1 gene is actively expressed in the corneal endothelium and is associated with posterior polymorphous corneal dystrophy type 3 (PPCD3)." (PMID 40244234, 2025). "ZEB1 loss-of-function (LoF) alleles are known to cause a rare autosomal dominant disorder—posterior polymorphous corneal dystrophy type 3 (PPCD3)." (PMID 33946386, 2021).
skin cancer (5 papers, 2014 to 2024). "Our previous finding revealed that PEBP impacted the formation of CSCs and decreased the migration and invasion of skin cancer cells by overexpression of miR-200b and inhibition of the transcription factor ZEB1." (PMID 38255297, 2024). "To explore this, we analyzed the correlation between FSTL1 and the EMT marker ZEB1 expression in various squamous cancers, skin tumors, and sun-exposed/unexposed skin using data from TCGA and GTEx." (PMID 38605354, 2024). "Our previous results revealed the effectiveness of PEBP in inhibiting CSC formation and suppressing cellular motility and invasiveness by upregulating miR-200b and downregulating ZEB1 in skin cancer cell lines." (PMID 36835085, 2023).
anaplastic thyroid cancer (4 papers, 2013 to 2021). "ZEB1 showed higher levels, as opposed to E-cadherin lower levels, in anaplastic thyroid cancer when compared to papillary and follicular thyroid cancer." (PMID 34680488, 2021).
asthma (4 papers, 2021 to 2025). "We found PDCD11 was negatively associated with asthma-related TFs, including WT1, ZEB1, and RERE; ALDH18A1 was negatively associated with WT1 and RERE; SEC61A1 was negatively related with WT1 and ZEB1." (PMID 35169275, 2022). "Interestingly, asthma-related TFs, including WT1, ZEB1, and RERE, were negatively associated with most of hub genes." (PMID 35169275, 2022). "In asthma, during airway smooth muscle (ASM) remodeling, IL-17, through the ZEB1 pathway, reduces the expression of E-cadherin and increases the expression of vimentin, promoting the thickening of the ASM layer driven by Th17 cells in severe asthma." (PMID 40016707, 2025). "CXCL10 was upregulated in asthma and LCP1, CCR1, PRKCB, IRAK2, LILRA1, and ZEB1 were significantly upregulated in COPD patients." (PMID 36829591, 2023). "We identified SLC7A11, SLC2A12, ZEB1, ATF3, and HIC1 common between DEGs and TFs involved with asthma and ferroptosis." (PMID 34257337, 2021). "The network analysis revealed that transcription factor (TF) WT1, ZEB1, RERE, FOSL1, and miR-20a may be involved in the development of asthma." (PMID 35169275, 2022).
Cirrhosis (4 papers, 2015 to 2025). A chronic disorder of the liver in which liver tissue becomes scarred and is partially replaced by regenerative nodules and fibrotic tissue resulting in loss of liver function. "No clinical factors, including age, sex, HBsAg status, microvascular invasion, tumor size, cirrhosis status, histological grade, AFP level, tumor encapsulation status and early recurrence status, were significantly associated with the upregulation of ZEB1 expression in HCC." (PMID 34234851, 2021). "ZEB-1 and vimentin were significantly upregulated, whereas correspondingly E-cadherin was significantly downregulated in HCC compared to non-cancerous liver specimens with and without cirrhosis." (PMID 26447841, 2015).
colorectal adenocarcinoma (4 papers, 2013 to 2021). The most common type of colorectal carcinoma. "Analysis of The Cancer Genome Atlas (TCGA)-generated colorectal adenocarcinoma data (two cancer studies; TCGA, Nature 2012, and TCGA, Provisional) showed that expression of ZEB1 is lower than or comparable to that of ZEB2." (PMID 29416649, 2018).
gastric tumor (4 papers, 2020 to 2025). "Consistent with the experimental results in cell lines, indisulam also increased the ZEB1 mRNA level in gastric tumor tissues." (PMID 36805336, 2023). "Concordantly, indisulam attenuated ZEB1 protein level in all three tested gastric tumor tissues." (PMID 36805336, 2023). "Finally, we show that treatment of gastric tumor samples with indisulam significantly reduces ZEB1 protein levels." (PMID 36805336, 2023). "Zinc finger E-box Binding homeobox 1 (ZEB1) is one of these genes which has been shown to promote metastasis and develop invasion in various cancer types including breast, prostate, colorectal, ovarian and gastric tumors 6–10." (PMID 32153739, 2020).
hypospadias (4 papers, 2019 to 2025). Hypospadias is the displacement of the urethral meatus on the ventrum of the penis. "mRNA and protein expression levels of the ZEB1 gene, a gene responsive to oestrogen that has been associated to isolated hypospadias, were found significantly upregulated in patients with severe hypospadias in comparison to patients with mild hypospadias." (PMID 33312738, 2020). "They indicated that there were low levels of miR-200c expression in hypospadias penile tissues, resulting in the high expression of the Zeb1 gene and protein, thereby activating the TGF-b/Smad3 pathway." (PMID 39624466, 2025). "Androgen and estrogen receptors as well as molecules responsible for their regulation, notably ZEB1, are expressed differently in skin of hypospadias patients." (PMID 31718599, 2019).
meningioma (4 papers, 2016 to 2021). A generally slow growing tumor attached to the dura mater. "Immunohistochemistry and real-Time-PCR, performed on 85 cases of various histopathological subtypes and grades of malignancy found significantly increased expression of Zeb-1 associated to aggressive WHO grade II or III meningiomas." (PMID 33915799, 2021). "Moreover, comparing aggressive grade II or III meningiomas with grade I tumors, loss of Zo-1 and E-Cadherin together with increased expression of Zeb-1 and Slug were observed, indicating that molecular features of EMT are present in aggressive meningiomas." (PMID 32244473, 2020). "Another investigation utilizing microarray analysis and bioinformatics also revealed that ZEB1 was significantly upregulated in malignant meningioma tissues and that its regulation involved miR-4652-3p." (PMID 33915799, 2021). "Analyzing 85 meningiomas of various grade and type, were observed reduced expression of EMT-linked transcription factors such as Twist, Zeb-1 and Slug." (PMID 32244473, 2020). "miR-200a-3p appears to act as a multifunctional tumor suppressor miRNA in meningioma, which might be related to ZEB1 and E-Cadherin." (PMID 27285757, 2016).
metastatic melanoma (4 papers, 2016 to 2025). A melanoma that has spread from its primary site to another anatomic site. "Immunohistochemical analyses of a metastatic melanoma sample from the patient, from whom the ESP cells were established, revealed low ZEB1 and TWIST1 protein levels before treatment (Fig EV1C), confirming the increase in ZEB1 expression upon acquisition of resistance to vemurafenib." (PMID 27596438, 2016).
multiple sclerosis (4 papers, 2022 to 2025). A progressive autoimmune disorder affecting the central nervous system resulting in demyelination. "ZEB1 suppression in T-cells alleviates the development and severity of symptoms in an animal model of autoimmune inflammatory diseases, while the downregulation of ZEB1 reduces pathogenic cytokine expression in T-cells from patients with multiple sclerosis." (PMID 41148802, 2025). "In multiple sclerosis (MS), a prototypical organ-specific autoimmune disorder, downregulation of ZEB1 effectively suppresses STAT3 phosphorylation and subsequent IL-17 expression, thereby attenuating the differentiation of pathogenic Th17 cells." (PMID 40016707, 2025). "In a model system to study multiple sclerosis, ZEB1 is suggested as a regulator of experimental autoimmune encephalomyelitis." (PMID 36040971, 2022). "The role of ZEB1 in the modulation of NSC function, particularly under neuroinflammatory conditions, makes it an attractive target for NSC-based therapies in various neurological disorders, such as multiple sclerosis, traumatic brain injury, and neurodegenerative diseases." (PMID 41148802, 2025).
neuroblastoma (4 papers, 2015 to 2022). Neuroblastoma (NB) is the most common solid, extracranial childhood tumor. "For example, overexpression of miR-200 repressed expression of a mesenchymal marker, Zeb1, and increased expressions of the epithelial markers, E-CDH and ZO-1, in a neuroblastoma cell line, SHSY5Y." (PMID 29440989, 2018).
ovarian tumor (4 papers, 2011 to 2025). "We demonstrate that MECOM promotes proliferation and migration of MECOM-amplified ovarian tumor cells by regulating KRAS/pERK1/2/ ZEB1 signaling cascade." (PMID 40664642, 2025). "A previous study confirmed that high expression of ZEB1 induces polarization of TAMs and promotes ovarian tumor growth." (PMID 31584877, 2019).
retinoblastoma (4 papers, 2019 to 2022). A malignant tumor that originates in the nuclear layer of the retina. "In this study, advanced Rb tumors showed increased expression of EMT signatures (ZEB1, FC = 92, p < 0.05; SNAI2, FC = 5.57, p < 0.05), which was a consequence of miR-181a-5p downregulation, as an EMT trigger." (PMID 36291907, 2022). "In both cell lines, reduction in ZEB1 and Snail protein expression was paralleled by inhibition in the ability of the retinoblastoma cells to invade Matrigel: between 50 to 80% reduction in transwell invasion was observed upon suppression of Nodal." (PMID 31451106, 2019). "The EMT program through ZEB1 is known to drive cellular mobility and tumor dissemination in other cancer systems; however, their role in EMT-driven drug resistance in Rb tumors is unknown." (PMID 36291907, 2022). "Immunofluorescence analysis of FFPE specimens of Rb tumors detected strong ZEB1 and cathepsin L positivity in advanced Rb tumor tissues compared with non-advanced Rb." (PMID 36291907, 2022). "However, ZEB1 (FC = 77.2, p < 0.05), SNAI2 (FC = 3.32, p < 0.05), ABCB1 (FC = 4.4, p < 0.05), and CTSL (FC = −3.8, p < 0.05) expressions were significantly downregulated in non-advanced Rb tumors." (PMID 36291907, 2022).
Alport syndrome (3 papers, 2009 to 2022). A rare renal disease characterized by glomerular nephropathy with hematuria progressing to end-stage renal disease (ESRD), frequently associated with sensorineural deafness, and occasionally with ocular anomalies. "ZEB1 mutations have been systemically linked with Alport syndrome and the progression of certain tumours." (PMID 36613650, 2022). "A complex binding site for ZEB1 protein exists in the promoter of a collagen gene, COL4A3, which is linked to the autosomal recessive form of Alport syndrome." (PMID 19997581, 2009).
ameloblastoma (3 papers, 2019 to 2025). The most common odontogenic tumor, arising from the epithelial component of the embryonic tooth and usually affecting the molar-ramus region of the mandible or maxilla. "Another transcription factor that can induce EMT and that has been implicated in the malignant transformation of ameloblastoma is the zinc finger E-box binding homeobox 1 (ZEB1)." (PMID 39430655, 2024). "We found that hypoxia‐induced HIF‐1a and ZEB1 are critical for the malignant transformation of ameloblastoma via TGF‐beta‐dependent EMT." (PMID 31674718, 2019). "Malignant transformation of ameloblastoma has been attributed to hypoxia-induced HIF-1α and ZEB1 expression via TGF-β-dependent EMT." (PMID 39430655, 2024).
benign prostatic hyperplasia (3 papers, 2013 to 2020). A non-cancerous nodular enlargement of the prostate gland. "Similarly, positive immunostaining of Zeb1 protein could be found in a small percent of CK14+ basal cells in human prostate tissues (non-benign prostate hyperplasia (non-BPH) (n = 3) and BPH specimens (n = 7))." (PMID 32024836, 2020). "The previous studies showed that TGF-β1 induces the expression of ZEB1, ZEB2, and SLUG, but not SNAI in benign prostatic hyperplasia epithelial cell line BPH-1 Cells." (PMID 24402783, 2014).
brain cancer (3 papers, 2017 to 2022). A primary or metastatic malignant neoplasm affecting the brain. "A study by Kahlert et al50, used surgical specimens of pediatric and adult brain cancers to show that ZEB1 expression was significantly increased in more invasive tumors." (PMID 32309604, 2018). "We have identified ZEB1 as a stem cell regulator in brain cancer which when deleted leads to increased stemness, tumorigenicity and shortened patient survival." (PMID 28246407, 2017).
Cerebral ischemia (3 papers, 2022 to 2025). Restriction of arterial blood supply to the brain associated with insufficient oxygenation to support the metabolic requirements of the tissue. "After cerebral ischemia, ZEB1 is highly expressed in microglia and highly associated with its larger branched morphology, which favors the pro-inflammatory phenotype." (PMID 40289984, 2025). "Conversely, ZEB1 induction promotes neuroprotection and cell survival in the neocortex after cerebral ischemia." (PMID 40289984, 2025). "These proteins include BPTF and MEF2C, which govern microglial homeostatic responses; MEF2A, which promotes autophagy; and ZEB1, which mediates protective effects after brain ischemia (Set 2)." (PMID 38178204, 2024). "ZEB1 was induced in response to cerebral ischemia and is involved in neuronal cell survival, while its upregulation in microglia associated with alleviating post-AIS cerebral injury by reducing neuroinflammation." (PMID 36613546, 2022).
colitis (3 papers, 2023 to 2024). Inflammation of the colon. "Together, our analyses demonstrate that loss of Zeb1 in fibroblasts induces sensitivity to ICB in both colitis-induced and sporadic tumor models." (PMID 38937629, 2024). "SNAI1 has been demonstrated to induce ZEB1 expression and is a potential repressor of E-cadherin and several tight junctions (CLDN1, OCLN, ZO-1) in IECs thereby promoting intestinal barrier dysfunction upon colitis and tumorigenesis in mice." (PMID 37174625, 2023).
corneal endothelial dystrophies (3 papers, 2010 to 2024). "Since ZEB1 mutations are identified in endothelial dystrophies, ZEB1 may be involved in retaining endothelial cell density and thereby corneal transparency." (PMID 33923743, 2021). "Considering this variability in expression, all cases of endothelial dystrophies should be screened for the presence of SLC4A11 and/or ZEB1 changes for confirmation and categorization." (PMID 21203343, 2010).
endothelial dysfunction (3 papers, 2018 to 2025). In vascular diseases, endothelial dysfunction is a systemic pathological state of the endothelium (the inner lining of blood vessels) and can be broadly defined as an imbalance between vasodilating and vasoconstricting substances produced by (or acting on) the endothelium. "Moreover, miR-200c and other family members are oxidative stress-induced miRNAs that promote downmodulation of ZEB1 and are implicated in endothelial dysfunction, causing apoptosis and senescence in endothelial cells." (PMID 36288146, 2022). "The expression of the genes encoding EndoMT transcription factors (SNAI1, SNAI2, TWIST1, and ZEB1), which are generally upregulated at endothelial dysfunction, also showed ≥2-fold increase after PA-BSA treatment, in particular the TWIST1 (≈eight-fold increase) and SNAI1 genes (≈four-fold increase)." (PMID 41465574, 2025).
gallbladder cancer (3 papers, 2016 to 2021). "For instance, ZEB1 expression was elevated in the tumor invasion front of gallbladder cancer tissues, which could be associated with the migration of tumor cells." (PMID 34796112, 2021). "A previous study showed that ZEB1 suppresses the expression of CDH13 (T-cadherin) in gallbladder cancer cells." (PMID 27818995, 2016). "Overexpression of ZEB1 and Zeb2 in epithelial cells have been demonstrated to induce the EMT, and ZEB1 is expressed at high levels in invading lung, uterine, colorectal, endometrial, prostate, and gallbladder carcinomas." (PMID 32730336, 2020).
gynecological cancer (3 papers, 2023). "The abnormal expression of ZEB1 in many cancers promotes progression, and high ZEB1 expression promotes the progression of gynecological cancer." (PMID 38070058, 2023). "Besides, targeting some transcription factors, including STAT3, Wnt, β-catenin, and ZEB1 might be a suitable strategy against gynecologic cancers." (PMID 37310654, 2023).
heart failure (3 papers, 2020 to 2024). Inability of the heart to pump blood at an adequate rate to meet tissue metabolic requirements. "In addition, miR‐183‐5p has been confirmed to be suppressed by ZEB1, which was associated with the development of cardiac hypertrophy and heart failure." (PMID 36988055, 2023). "The predictive value of miR-200b-3p and ZEB1 in the prognosis of heart failure was evaluated by analyzing the receiver operating characteristic (ROC) curve." (PMID 38702771, 2024). "Specifically, TSC-Exos exerted an antiapoptotic and anti-inflammatory effect by decreasing the expression of Zeb1 and some inflammatory cytokines, which provided an alternative mechanism of reversing chemotherapy-induced heart failure." (PMID 33218341, 2020).
intestinal tumors (3 papers, 2016 to 2024). "Thus, and in contrast to the well-established role of ZEB1 as a pro-invasive and prometastatic factor, ZEB1 inhibited the metastatic liver and lung dissemination of intestinal tumors in BrafV600E mice." (PMID 37870961, 2023). "ZEB1 inhibits metastatic dissemination of intestinal tumors in BrafV600E mice." (PMID 37870961, 2023). "The downregulation of Zeb1 in Kras-mutant mice (KVZ+/–) reduced both the number and size of the intestinal tumors formed relative to Kras-mutant mice with basal levels of Zeb1 (KVZ+/+)." (PMID 37870961, 2023). "Furthermore, intestinal type tumors showed significantly reduced ZEB1 expression in tumor cells, higher tumor budding at the invasive front as well as reduced CAF activation grade compared to non-intestinal tumors." (PMID 26951071, 2016).
ovarian serous carcinoma (3 papers, 2015 to 2021). "Another study assessed the protein expression of E-CADH, N-CADH, P-cadherin, ZEB1, HMGA2, RAB25, CD24, NCAM, SOX11, and VIM in 100 tubo-ovarian serous carcinoma effusions and found a limited prognostic role of the markers alone or in combination." (PMID 34070214, 2021).